IL6 (interleukin 6)
Diseases named in the same sentence as IL6 in open-access papers (continued):
Sharing a sentence is not in itself a finding about the gene and the disease.
carotid atherosclerosis (37 papers, 2010 to 2025). A thickening and loss of elasticity of the walls of carotid arteries that occur with formation of atherosclerotic plaques. "Increased levels of IL-6 and sLOX-1 were associated with a risk of progression of carotid atherosclerotic disease." (PMID 37627316, 2023). "Accordingly, we have recently reported that HCWs with a “dysfunctional circadian clock” and with increased levels of IL1b carry a higher risk of developing carotid atherosclerosis through an overload of IL6 being released." (PMID 35886686, 2022). "Our work supports this assumption showing the association of the C allele in IL6-174 G>C SNP with carotid atherosclerosis in the irradiation context." (PMID 27662210, 2016). "This suggests an association between carotid atherosclerosis and the local production of not only IL-6 but also E-selectin, VCAM-1 and PTX3." (PMID 24936646, 2014). "In addition, NLRP3 inflammasomes are closely associated with colchicine, IL-1β, and IL-6 and are thought to be potentially important targets for anti-inflammatory treatment of atherosclerotic heart disease." (PMID 33598482, 2020). "The IL6-174 CC genotype confers a three-fold risk for carotid atherosclerotic disease suggesting it may represent a genetic susceptibility factor in the LDR context." (PMID 27662210, 2016). "Elevated IL-6 levels appear to be associated with lower echogenicity of carotid plaques, unstable plaques and internal carotid artery stenosis in several observational studies, suggesting a link between IL-6 and the pathogenesis and progression of carotid atherosclerosis." (PMID 36060677, 2022). "First, the IL6 genetic proxy was robustly associated with lower risks of CAD, PAD, atherosclerotic stroke and carotid atherosclerosis across European and East Asian ancestry populations." (PMID 40858837, 2025). "Numerous studies have shown that inflammatory factors [tumor necrosis factor alpha, interleukin (IL)-1, and IL-6 levels] are elevated in patients with atherosclerotic heart disease." (PMID 37476576, 2023). "A study on carotid atherosclerosis showed that blood levels of IL-6 and TNFα were higher in patients with carotid atherosclerosis compared to control subjects and the cytokine levels increased with increasing amounts of carotid atherosclerosis stenosis." (PMID 35600479, 2022). "Thus, it is logical that the IL-6/IL6R gene polymorphisms could affect carotid atherosclerosis." (PMID 36060677, 2022). "There was an association between RA patients who harbored carotid atherosclerosis and inflammatory markers such as CRP*, ESR* and IL-6** and VCAM-1*, a marker of endothelial impairment (*p<0.001 and **p<0.05)." (PMID 36249997, 2022). "We have evaluated the association of the IL6-174 G>C SNP with late effects of LDR (TC, BCC and carotid atherosclerotic disease) in a cohort of individuals irradiated in childhood for tinea capitis treatment." (PMID 27662210, 2016). "In our study we assessed the association of the IL6-174 G>C SNP with TC, BCC and carotid atherosclerosis in the Portuguese tinea capitis cohort." (PMID 27662210, 2016). "Firstly, a cardiovascular risk study showed that the polymorphism of the interleukin-6 promoter gene is associated with markers of subclinical carotid atherosclerosis in males, but not significantly in females." (PMID 39479392, 2024). "The Cardiovascular Risk in Young Finns Study also reported that the IL-6 promoter gene polymorphism (IL6-174 G>C) was associated with markers of subclinical carotid atherosclerosis in men, but not significant in women." (PMID 36060677, 2022). "We found that the IL6-174 CC genotype confers a three-fold risk for carotid atherosclerotic disease compared with non-irradiated individuals." (PMID 27662210, 2016). "Among these, IL-6 and TNF-α are key pro-inflammatory cytokines involved in all stages of carotid atherosclerosis—from plaque formation and progression to rupture." (PMID 40963681, 2025).
carotid atherosclerosis (continued). "Serum GRB2 was found to be positively correlated with C-reactive protein and interleukin-6 levels, which were higher in patients with T2DM (compared to the healthy population), and further increased in patients with T2DM with carotid atherosclerosis." (PMID 39408563, 2024). "Another study identified a connection between the IL-6 GG (rs1800795) genotype and increased CIMT in asymptomatic individuals with carotid atherosclerosis." (PMID 37838929, 2024). "Serum IL-6 levels and disease activity (SLEDAI-2K), severity (Katz) and damage index (SLICC-DI), complete lipid profile, and subclinical carotid atherosclerosis were evaluated in 284 patients with SLE." (PMID 37762312, 2023). "In a recent smaller study, IL-1β and IL-6 were found higher expressed in pericoronary artery adipose tissue, probably comparable with the EAT in our study, in patients with atherosclerotic heart disease compared to controls with mitral valve surgery." (PMID 36644557, 2022). "Inflammatory cytokines such as interleukin-6 (IL-6), tumor necrosis factor-α, and hs-CRP are well-established markers of carotid atherosclerosis." (PMID 24192205, 2013). "Furthermore, PLWH with carotid atherosclerosis showed greater inflammatory activation, as evidenced by elevated serum IL-6 concentrations, compared to those without arterial injury." (PMID 40718411, 2025).
giant cell arteritis (37 papers, 2013 to 2026). "In addition, in patients with scleritis associated with giant cell arteritis, anti-IL6 drugs have been tested in those with several relapses, corticosteroid dependence and resistance to methotrexate." (PMID 37063831, 2023). "Treatment with corticosteroids was initiated, followed by the introduction of weekly subcutaneous tocilizumab, an IL-6 inhibitor, ultimately resolving both his APS and its underlying cause, giant cell arteritis." (PMID 41170209, 2025). "Regarding results obtained in giant cell arteritis with IL-6 inhibitors, a cytokine involved in Th17 differentiation, the use of anti-IL-17 is a promising strategy." (PMID 35479069, 2022). "IL6 is a pleiotropic cytokine and studies have demonstrated that IL-6 plays a crucial role in the pathophysiology of Takayasu arteritis and giant cell arteritis." (PMID 33505509, 2021). "Sirukumab, an anti-IL-6 monoclonal antibody, has shown the efficacy in decreasing disease flares of giant cell arteritis in a phase 3 trial with early termination." (PMID 34066203, 2021). "In support of this theory, a previous study showed that NFAT1 activation increased the expression of IL6 and promoted the pathogenesis in giant cell arteritis." (PMID 29258522, 2017). "Systemic vasculitides with increased IL-6 expression include Takayasu’s arteritis, acute Henoch-Schönlein purpura, giant cell arteritis, acute Kawasaki disease, and various large vessel vasculitides." (PMID 28289923, 2017). "Recent introduction of interleukin-6 signaling blocker, tocilizumab has substantially changed the practice in management of patients with LVV, in particular, giant cell arteritis (GCA)." (PMID 38125643, 2023). "Dendritic cells drive the inflammatory process and IL1, IL6 and IL21 are highly expressed in giant cell arteritis (GCA)." (PMID 35250864, 2022). "Takayasu arteritis and giant cell arteritis (GCA), chronic and potentially life-threatening inflammatory diseases of the blood vessels, are further examples where IL-6 plays a pivotal role in disease progression." (PMID 36140141, 2022). "Pro-inflammatory cytokine mRNA, including IL-6, has been identified from temporal artery specimens of patients with PMR; however, mRNA for IFN-γ has not been found, indicating that IFN-γ might have a role in the progression of subclinical vascular inflammation to overt arteritis." (PMID 31431999, 2019).
leukopenia (37 papers, 2010 to 2026). "Indeed, despite profound leukopenia and a deficit of circulating immune cells, NE patients exhibited a high level of circulating proinflammatory cytokines, particularly IL-6." (PMID 40380332, 2025). "Despite leukopenia, NE is associated with a local immune activation via the IL-6 and the OSM-OSMR pathways, which is not driven by neutrophils." (PMID 40380332, 2025). "Another contributing factor may be the severe leukopenia caused by the virus, with a significant decrease in the number of CD4 and CD8 lymphocytes and elevation of interleukins (IL-2R, IL-6, IL-10, TNF-alpha) and other inflammatory markers." (PMID 35205852, 2022). "Elevated D-dimer, platelet counts, IL-6, and leukopenia were observed." (PMID 34944606, 2021). "Severity of CLP in cGAS-/- mice was less severe than in wildtype (WT) mice, as indicated by mortality, serum LPS, cfDNA, leukopenia, cytokines (TNF-α, IL-6 and IL-10), organ histology (lung, liver and kidney) and spleen apoptosis." (PMID 34768881, 2021). "Notably, AKT1, EGFR, IL6, STAT3, BCL2, CASP3, and JUN were identified as the top seven targets (degree >80) and may be key targets of QJSB in treating leukopenia." (PMID 39295929, 2024).
peripheral nerve injury (37 papers, 2009 to 2025). Injury to a peripheral nerve. "In summary, the present study offers insights into the underlying mechanism of widespread pain induced by peripheral nerve injury, specifically focusing on the role of CSF containing IL-6." (PMID 38419042, 2024). "IL-6 also appears to be associated with NP, with animal studies indicating a local increase in the mRNA and protein levels of IL-6 following peripheral nerve injury." (PMID 39618549, 2024). "IL-6 is implicated in mediating the enhanced regenerative activity of DRG neurons after a peripheral nerve injury." (PMID 29279307, 2018). "Recently, converging lines of evidence have indicated that IL-6 plays a critical role in neuropathic pain caused by peripheral nerve injury, SCI, and chemotherapy-induced peripheral neuropathy." (PMID 27267059, 2016). "After peripheral nerve injury, microglial cells are activated by molecular mediators such as neuregulin-1, chemokine (C–C motif) ligand 2, and fractalkine; activated microglial cells in turn release IL-6, IL-1β, and TNF-α to cause painful symptoms." (PMID 36348269, 2022). "Pro-inflammatory interleukins, such as IL-1β, IL-6, and IL-17, play a pivotal role in the pathophysiology of peripheral nerve injury." (PMID 41573554, 2025). "Studies in rodent models of diabetic peripheral nerve injury have indicated that blocking pro-inflammatory interleukin-6 (IL-6) and tumor necrosis factor-α (TNF-α) expressions attenuates neuroinflammatory response and pathological damage." (PMID 41264657, 2025). "In peripheral nerve injury, the pro-inflammatory cytokine IL-6 plays a critical role in modulating nerve repair and regeneration through various mechanisms." (PMID 41573554, 2025). "Of course, it cannot be ignored that interleukins exhibit a time-dependent bidirectional effect in the repair of peripheral nerve injury, such as factors like IL-1β, IL-6, and IL-17." (PMID 41573554, 2025). "IL-6 is predominantly induced as challenged by PGE2 and TNF-α in peripheral nerve injury, and is implicated in neuropathic pain via MAPK and STAT3 signaling." (PMID 38419042, 2024). "In SC, proinflammatory cytokines IL-1β and IL-6 have been generally reported to be increased after peripheral nerve injury." (PMID 36830952, 2023). "Numerous studies have reported increased spinal levels of pronociceptive IL-6 following peripheral nerve injury, which is consistent with our results." (PMID 35056145, 2022). "In the setting of peripheral nerve injury, IL-6 has been shown to contribute to nerve ending sprouting." (PMID 35262711, 2022). "Previous reports suggest that increased production of pronociceptive interleukins (e.g., IL-1β, IL-18, and IL-6) by immune and glial cells after peripheral nerve injury contributes to the development and maintenance of neuropathic pain." (PMID 34681732, 2021). "The cytokines IL6, TNF, IL10, IL2, and IL4 are all immunomodulatory factors, among which TNF and IL-6 have been confirmed to be involved in the pathological process of peripheral nerve injury." (PMID 33299447, 2020). "IL-6 is elevated in several models of peripheral nerve injury, and targeting IL-6 attenuates neuropathic pain." (PMID 33063247, 2020). "Stat3 inhibitors are used to treat peripheral nerve injury-induced hyperexcitability within dorsal horn neurons, pain behaviors, chronic constriction injury, and signaling of IL-6 cytokines." (PMID 32038157, 2019). "Several studies have indicated that IL-6, which is secreted mostly by macrophages and activated microglia, is strongly increased after peripheral nerve injury." (PMID 28337574, 2017). "Most studies have used an animal model of peripheral nerve injury to explore the relationship between IL-6 and neuropathic pain." (PMID 27267059, 2016). "Recently, the clinical involvement of IL-6 in peripheral nerve injury-induced pain was also reported." (PMID 27267059, 2016).
peripheral nerve injury (continued). "Moreover, in peripheral nerve injury, IL-6, IL-6R, and gp130 (a signal transducer of IL6R) are overexpressed, making it possible to cause significant pain hypersensitivity." (PMID 32867013, 2020). "The increased levels of IL-6 in the spinal cord after peripheral nerve injury may participate in neuropathic pain development." (PMID 27221523, 2016). "In case of peripheral nerve injury, the damaged neurons send excitatory signals to the spinal microglia via chemical substances, such as ATP and chemokines; these, in turn, cause microglial proliferation and upregulation of inflammatory cytokines, such as TNF-α, IL-1β, and IL-6, resulting in NP." (PMID 32636748, 2020). "The expression of TNF-α, IL-6, and other pro-inflammatory factors in the DRG have been found to be increased after peripheral nerve injury." (PMID 35493326, 2022). "Peripheral nerve injury activated a characteristic set of signaling pathways in both sexes, including HMGB1 Signaling, TREM1 signaling, IL-6 Signaling, IL-17 Signaling, Integrin signaling, HIF1α Signaling, Oxytocin Signaling, and ILK Signaling." (PMID 34966260, 2021). "SC, the most abundant peripheral glial cells, respond to peripheral nerve injury by the way of changing phenotype and releasing of inflammatory mediators (TNF-α, IL-6, and IL-1β), which leads to the exacerbation of NP." (PMID 34630095, 2021). "In addition, they further demonstrated that an intrathecal injection of anti-IL-6 antibody could attenuate L5 spinal nerve transection-induced mechanical allodynia, providing further evidence for the role of central IL-6 in the etiology of mechanical allodynia following peripheral nerve injury." (PMID 27267059, 2016). "During Wallerian degeneration after peripheral nerve injury, pro-inflammatory cytokines, such as TNF-α, IL-1, and IL-6, are produced in the distal stump and/or recruited through circulation." (PMID 26629691, 2015). "We chose three IL-6-type cytokines IL-6, CNTF, and LIF because these three factors are known as “injury factors” that are induced after peripheral nerve injury and have been studied regarding their effects on CNS regeneration." (PMID 25162623, 2014). "Therefore, IL-6 released into the CSF can further activate STAT3, amplifying the inflammation responses and facilitating of the propagation of pain following peripheral nerve injury." (PMID 38419042, 2024). "Altogether, these results indicated that sNAMs are the main source of CX3CR1 signaling-dependent pro-inflammatory cytokines (e.g. IL-b and TNF) in the sensory ganglia after peripheral nerve injury, whereas IL-6 seems to be induced mainly in non-immune cells." (PMID 37254842, 2023). "Nevertheless, our data indicate that sNAMs are not the source of IL-6 after peripheral nerve injury." (PMID 37254842, 2023). "Peripheral nerve injury leads to activation of corresponding DRG macrophages and local spinal cord inflammation through activation of glial cells, recruiting and releasing TNF-α, IL-6, or monocyte chemoattractant protein-1 by immune cells." (PMID 34813418, 2022). "Besides, several inflammatory mediators are produced as a response to peripheral nerve injuries, such as TNF-α and IL-6." (PMID 32867013, 2020). "Phosphorylation of STAT3 is a known consequence of peripheral nerve injury, and particularly noteworthy in the context of our study: several of the mediators we identified as up-regulated with nerve injury in mouse mural cells are cytokines which activate the JAK/STAT pathway (Il6, Lif and Clcf1)." (PMID 40381746, 2025).